Y_RNA (Y RNA )
Gene: Miscellaneous RNA gene on chromosome 2 (85,460,144 to 85,460,252, reverse strand). Ensembl gene ENSG00000199936.
Homologues: Orthologues: chimpanzee Y_RNA (98% identical), macaque Y_RNA (93% identical). Paralogues in human: RNY1 (93% identical), Y_RNA (91% identical), Y_RNA (89% identical), Y_RNA (88% identical), Y_RNA (87% identical), Y_RNA (86% identical), Y_RNA (85% identical), RNY1P11 (84% identical), Y_RNA (84% identical), Y_RNA (83% identical), RNY1P12 (83% identical), RNY1P8 (83% identical), and 97 more.